FOLR1 (folate receptor alpha)
Diseases named in the same sentence as FOLR1 in open-access papers (continued):
Sharing a sentence is not in itself a finding about the gene and the disease.
ovarian carcinoma (continued). "Folate receptor alpha (FR-α) is a glycosylphosphatidylinositol cell surface-anchored glycoprotein, overexpressed in 90% ovarian carcinomas and many types of epithelial cancers." (PMID 31334122, 2019). "We show that both conventional and chemically programmed CD3 × FOLR1 biAbs exert specific in vitro and in vivo cytotoxicity toward FOLR1-expressing ovarian cancer cells by recruiting and activating T cells." (PMID 31497024, 2019). "Some studies have developed that serum FOLR1 is a biomarker for ovarian cancer with implications for diagnosis, prognosis, and prediction of OC." (PMID 31049278, 2019). "Both conventional and chemically programmed CD3 × FOLR1 biAbs warrant further investigation for ovarian cancer immunotherapy." (PMID 31497024, 2019). "In this study, we determine the expression of FOLR1 in ovarian cancer and examine if FOLR1 levels influence response to cisplatin." (PMID 29433550, 2018). "Here, we show that increased expression of FOLR1 increases sensitivity of ovarian cancer cells to cisplatin." (PMID 29433550, 2018). "Our data show that high expression of FOLR1 in ovarian cancer cells increases sensitivity to cisplatin." (PMID 29433550, 2018). "In summary, we find that FOLR1 is highly expressed in ovarian cancer but is reduced following multidrug resistance." (PMID 29433550, 2018). "For example, they found low levels of certain markers that have been gaining traction as drug targets (EphA2), or that have been touted as specific for (MUC16 and FOLR1) or overabundant (Mesothelin) in ovarian cancer." (PMID 30011875, 2018). "FOLR1 knockdowns in ovarian cancer cells inhibited folate-mediated cellular proliferation and suppressed an invasive phenotype." (PMID 29874279, 2018). "Expression of FOLR1 in platinum drug-resistant ovarian cancer was lower than in platinum drug-sensitive tumors (P < 0.01),and after further chemotherapy expression of FOLR1 in PD was still lower than that in remission (p < 0.01)." (PMID 29433550, 2018). "Because the serum Folr1 protein secreted by tumor cells in soluble form has been referred as a biomarker of prognosis in ovarian cancer patients, we evaluated the soluble Folr1 in serum or CSF as an indicator for MB." (PMID 28416738, 2017). "In this retrospective study we evaluated the respective correlations and clinical relevance of FOLR1 mRNA expression, FOLR1 promoter specific methylation and global DNA hypomethylation in type I and type II ovarian cancer." (PMID 27485273, 2016). "The purpose of the study presented here was to analyse the clinical relevance of FOLR1 mRNA expression and its possible influence on global DNA methylation status in ovarian cancer." (PMID 27485273, 2016). "Two hundred fifty four ovarian cancers, 13 borderline tumours and 60 samples of healthy fallopian epithelium and normal ovarian epithelium were retrospectively analysed for FOLR1 expression with RT-PCR." (PMID 27485273, 2016). "The study presented here analysed FOLR1 mRNA expression, its promoter DNA methylation and global DNA hypomethylation in ovarian cancer and focused especially on differences between type I and type II cancers." (PMID 27485273, 2016). "FOLR1 was found to be strongly expressed in renal, pancreatic, endometrial carcinomas, squamous cervical cancer and ovarian cancer." (PMID 27485273, 2016). "We conclude that according to FOLR1 expression our data evidenced a completely different behaviour between type I and type II ovarian cancers in terms of clinical outcome and platinum sensitivity." (PMID 27485273, 2016). "Overexpression of folate receptor alpha (FRα) and high telomerase activity are considered to be the characteristics of ovarian cancers." (PMID 27026065, 2016). "Folate receptor alpha (FOLR1, a membrane-bound molecule) and mesothelin (MSLN, a glycosyl-phosphatidylinositol-linked cell surface antigen) that are upregulated in ovarian carcinoma are also upregulated in serous EC more frequently than in endometrioid EC." (PMID 23819113, 2013).
ovarian carcinoma (continued). "Nearly no information is available in regard to the signaling pathway of FOLR1 in ovarian cancer, but it was suggested it signals through p-53/lyn/Gαi-3." (PMID 23319948, 2012). "The folate receptor alpha (FRα) is one logical choice for a biomarker because of its prevalent overexpression in ovarian cancer and its exclusive expression in only a few normal tissues." (PMID 19617914, 2009). "Reliable testing of folate receptor alpha is essential to identify patients who may benefit from a targeted treatment for ovarian cancer." (PMID 41301065, 2025). "Additionally, FOLR1 or portions of the receptor are released into the circulation and function as serum markers for ovarian cancer." (PMID 40038575, 2025). "Additionally, Yang and colleagues generated patient-derived xenograft (PDX) models from 107 patient samples of osteosarcoma, 84 (78.5%) of which had detectable FOLR1 mRNA expression, some to the level of FOLR1 mRNA expression by an ovarian carcinoma cell line." (PMID 40919994, 2025). "The detection of BRCA1/2 mutations is routinely used as a strong predictor of response to PARP inhibitors, while HER2, TROP2, and FOLR1 expressions have emerged as primary targets for the treatment of recurrent ovarian cancer patients using novel antibody–drug conjugates (ADCs)." (PMID 40507303, 2025). "Accurate immunohistochemical evaluation of folate receptor alpha (FOLR1) expression is critical for identifying patients with ovarian carcinoma who may benefit from targeted therapy with Mirvetuximab Soravtansine." (PMID 40508029, 2025). "Our results could have important implications for the design of combination therapies comprising IMGN853 and other drugs for the treatment of ovarian cancer, as well as other types of FOLR1+ cancers." (PMID 40029935, 2025). "FOLR1 is heterogeneously overexpressed in epithelial ovarian cancer." (PMID 40029935, 2025). "Finally, different ovarian cancer cell lines were employed as target cells in in vitro co-culture experiments, namely OV-90, OV-90 FOLR1 KO, OVCAR-3, and SKOV-3." (PMID 39594628, 2024). "For further selection of scFv-Fc candidates, specificity thresholds were defined for on-target binding (>50% of Jurkat FOLR1 KI cells), off-target binding (<10% of on OV-90 FOLR1 KO cells), and on-tumor binding (>50% on-target binding on ovarian cancer tissue)." (PMID 39594628, 2024). "As an epithelial cell surface receptor, FOLR1 or its components may be shed into the circulation, making it a viable candidate as a serum marker for ovarian cancer." (PMID 40836974, 2024). "Besides a safety assessment in mice, future studies should address efficacy of the fully human anti-FOLR1 CAR in a relevant in vivo ovarian cancer model." (PMID 39594628, 2024). "We performed an additional co-culture experiment using anti-FOLR1 CAR T cell candidates co-cultured with ovarian cancer cell lines with varying FOLR1 expression levels, i.e., OVCAR-3 (FOLR1low), SKOV-3 (FOLR1intermediate), and OV-90 (FOLR1high), as well as OV-90 FOLR1 KO cells." (PMID 39594628, 2024). "Related experiments have shown that single-dose bispecific targeting of FOLR1 and death receptor 5 (DR5) is an effective strategy for treating ovarian cancer, suggesting FOLR1 may be a potential biomarker for ovarian cancer." (PMID 35719392, 2022). "Around 76% of high-grade ovarian cancer patients show a FOLR1 overexpression." (PMID 36233339, 2022).
ovarian carcinoma (continued). "This is consistent with the data showing the overexpression of folate receptor alpha (FRα) in ovarian cancer cells, a receptor that has a higher affinity for folic acid, which allows tumour cells to proliferate even in low folate environments by transporting folic acid into cells." (PMID 34680361, 2021). "Interestingly, previous RNA-seq data demonstrated that FOLR1, which has high expression in ovarian cancer, is differentially expressed in TSCC." (PMID 34295808, 2021). "Mouse/human chimeric IgE (MOv18) specific for the ovarian cancer antigen, folate receptor alpha (FRα)-mediated ADCC and ADCP of ovarian cancer cells (IGROV1) by human peripheral blood mononuclear cells (PBMCs), human monocytic U937 cells and peripheral blood monocytes and eosinophils." (PMID 33081206, 2020). "In ovarian carcinoma cells, FOLR1 was intensely studied, and it was confirmed that the folate receptor is abundant in the OVCAR-3 cell line; in A2780 cells, the folate receptor positive expression was confirmed, but the studies indicated a lower expression than in other malignant ovary cell lines." (PMID 32503320, 2020). "FOLR1 was reported to be overexpressed in ovarian cancer, and its expression could be regulated by both female sex hormones and retinoic acid." (PMID 31333395, 2019). "In contrast, the conventional biAb only saw FOLR1 on the xenografted human ovarian cancer cells." (PMID 31497024, 2019). "FOLR1 may be a useful biomarker for ovarian cancer, and it may be useful as a therapeutic application to improve sensitivity to cisplatin treatment." (PMID 29433550, 2018). "The data we provide here suggest that FOLR1 may be a useful predictive biomarker for cisplatin sensitivity in ovarian cancer." (PMID 29433550, 2018). "We hypothesize that changes in FOLR1 expression and folate metabolism directly or indirectly contribute to cisplatin-induced apoptosis in ovarian cancer and influence cisplatin sensitivity." (PMID 29433550, 2018). "We find that FOLR1 is particularly high in cases of ovarian cancer, which suggests that FOLR1 may be useful as a clinical diagnostic marker for the disease." (PMID 29433550, 2018). "We hypothesize that FOLR1 may promote ovarian cancer cell growth by transporting folic acid; it may also influence the response to cisplatin." (PMID 29433550, 2018). "In addition, the first clinical study using FOLR1-CAR T cells in patients with ovarian cancer has shown that it has performed well in terms of safety and efficacy." (PMID 29874279, 2018). "There have been a few studies regarding serum Folr1 as a biomarker for diagnosis in ovarian cancer." (PMID 28416738, 2017). "Importantly, CA125 and HE4 are present in this quadrant, as well as other proteins that have been reported to be elevated in the sera of women with ovarian cancer, such as interleukin-6, midkine, folate receptor-alpha, KLK6, and hK11." (PMID 29051715, 2017). "This evidence stems from prespecified subgroup analysis of a Phase 3 clinical trial testing farletuzumab, a monoclonal antibody to folate receptor alpha, plus standard-of-care carboplatin-taxane chemotherapy in patients with recurrent platinum-sensitive ovarian cancer." (PMID 28881712, 2017). "In the unselected cohort of examined ovarian cancers, FOLR1 mRNA expression with a median value of 9.14 (arbitrary units normalized to TBP) was significantly stronger than in borderline tumours (median value: 1.88; p = 0.01) and in healthy controls (median value: 0.49; p < 0.0001)." (PMID 27485273, 2016). "As such, researchers have also examined whether serum FOLR1 could be a potential marker for early detection of female-related cancers, notably ovarian carcinoma." (PMID 24810481, 2014). "The results further support that FOLR1 could be a potential biomarker in detection, prognosis, and assessing chemotherapy responses of ovarian carcinoma." (PMID 23319948, 2012).
ovarian carcinoma (continued). "Consequently, these studies support the upregulation of FOLR1 in ovarian cancer and confirm that it plays a significant role in regulating folate pathways in the tumor environment, making FOLR1 a possible biomarker for early detection of ovarian carcinoma." (PMID 23319948, 2012). "We studied the involvement of 11q markers in ovarian cancer by looking for tumour-specific loss of heterozygosity (LOH), as well as amplification or rearrangements that might explain the overexpression of FOLR1." (PMID 8094291, 1993). "Here, we will discuss key biomarkers with clinical relevance in ovarian cancer, namely breast cancer susceptibility genes 1 and 2 (BRCA), human epidermal growth factor receptor 2 (HER2), trophoblast cell surface antigen 2 (TROP2), and folic acid receptor alpha (FOLR1)." (PMID 40507303, 2025). "Folate receptor alpha is a glycosylphosphatidylinositol-anchored membrane protein responsible for folate uptake of cells and is highly expressed in several epithelial solid tumors, such as endometrial cancer, ovarian cancer, colorectal cancer, triple-negative breast cancer and lung cancer." (PMID 38730739, 2024). "Mirvetuximab soravtansine is an ADC comprising an IgG1 monoclonal antibody against the folate receptor alpha (FRα) conjugated to the cytotoxic maytansinoid effector molecule DM4 that has shown promising clinical activity in patients with FR-α-positive ovarian cancer." (PMID 37528890, 2023). "FRα (alternatively known as FOLR1) could be considered a favorable target antigen in the CAR-T therapy of ovarian cancer owing to its elevated level of expression in a high percentage of ovarian cancer cases." (PMID 38146364, 2023). "In patients with recurrent ovarian cancer, the antibody-drug conjugate mirvetuximab soravtansine co-administered with bevacizumab, has shown anti-tumor activity that leads to lasting responses in platinum “agnostic” cases (resistant/sensitive), with strong folate receptor alpha expression (FR-α)." (PMID 35448205, 2022). "Of note, the MOv18 IgE specific for the folate receptor alpha (FRα) was demonstrated to have anti-tumor effects in vitro and in vivo and is in phase 1 clinical trials testing with early data demonstrating demonstrated safety and efficacy in ovarian cancer patients." (PMID 35433433, 2022). "The FOLR1 expression is restricted to the luminal surfaces of the epithelial cells in healthy populations, but it is highly expressed in many epithelial cancers, including breast cancer, ovarian cancer, clear cell renal carcinomas, endometrial carcinomas, and lung cancer." (PMID 36233339, 2022). "DO analysis revealed that DEGs PSAT1, FOLR1, ABCB1, SFRP1, SFRP1, BUB1B have a greater association with female reproductive system tumor-related diseases, such as malignant ovarian surface epithelial-mesenchymal tumor, ovarian epithelial carcinoma, and ovarian cancer." (PMID 35719392, 2022). "In ovarian cancer, FRα may or may not be associated with FOLR1 gene amplification (chromosome 11q13.3)." (PMID 35008360, 2021). "Thus, the in vivo performance of the chemically programmed biAb in the mouse model may provide a more realistic assessment of the potential of CD3 × FOLR1 biAbs in ovarian cancer patients." (PMID 31497024, 2019). "Flow cytometric analysis showed differential expression of FOLR1, TROP2, and TF in ovarian cancer cells." (PMID 41585490, 2026). "In this study, electrochemical-based panel immunosensors were prepared for the simultaneous determination of four potential biomarkers of ovarian cancer (AGR2, GLY, FOLR1, and SMRP)." (PMID 41518408, 2026). "For the first time in this study, an electrochemical panel immunosensor system was prepared using HSPEs for the simultaneous determination of potential ovarian cancer biomarkers AGR2, GLY, FOLR1, and SMRP." (PMID 41518408, 2026).
ovarian carcinoma (continued). "ElahereTM (mirvetuximab soravtansine), the first FDA-approved folate receptor alpha (FRα)-targeting ADC, is remarkably effective in patients with platinum-resistant ovarian cancer." (PMID 41155607, 2025). "Exploratory markers FOLR1 and MUC1 had subtle increases for cancer groups, with early-stage ovarian cancer samples having the smallest effects." (PMID 40801326, 2025). "In this study, we developed five NIR-PIT agents by conjugating scFv-SNAP-tag fusion proteins with BG-modified IRdye700 to target ovarian cancer cells, which expressed cell surface antigens epidermal growth factor receptor (EGFR), Her2, FOLR1, TROP2, and TF." (PMID 41362788, 2025). "We have developed bispecific biologics in an IgG-extended format that bind both to Folate Receptor alpha (FOLR1), which is highly expressed in the majority of ovarian cancers, and to the activating butyrophilin (BTN)3A." (PMID 40755782, 2025). "Although FOLR1, NaPi2b, TROP2, and others are highly expressed in ovarian cancer, there are differences among different pathological types of epithelial ovarian cancer." (PMID 40046734, 2025). "To evaluate the impact of IMGN853 on FA uptake in ovarian cancer cells, we used Alexa Fluor 488–FA–conjugated submicrogels in SKOV3 cells, which are known for their high FOLR1 expression." (PMID 40029935, 2025). "In this study, we used scFv-SNAP-tag, targeting ovarian cancer cells expressing EGFR, Her2, FOLR1, TROP2, and TF antigen to generate 1:1 antibody IR700 ratio, which is important to get robust pharmacokinetic, efficacy, and safety profiles." (PMID 41362788, 2025). "Five cancer antigen-specific NIR-PIT agents targeting EGFR, Her2, FOLR1, TROP2, and TF were developed to selectively kill ovarian cancer cells." (PMID 41362788, 2025). "From a broader molecular profiling viewpoint, the key determinants for guiding personalised, nanoparticle-enabled therapy in ovarian cancer are highlighted as multi-omic profiling of BRCA/HRD, HER2, FOLR1 and other targets." (PMID 41514600, 2025). "After designing a library of FOLR1-directed CAR T cells, their functionality and specificity were assessed in vitro against cell lines as well as in vivo in a mouse model of ovarian cancer." (PMID 38254822, 2024). "Evaluating the prognostic and predictive value of the FOLR1 high-like signature and of RFC expression in large prospective cohorts of ovarian cancer patients treated with mirvetuximab soravtansine and novel strategies is warranted." (PMID 39596024, 2024). "We first confirmed that gene expression of FOLR1 (for FRα) and of members of the folate signalling pathway (FOLH1, TYMS and DHFR), were elevated in ovarian cancer cell lines and ovarian cancer tissues, compared to normal tissues." (PMID 36402875, 2023). "We selected folic acid receptor alpha (FOLR1), a glycosylphosphatidylinositol (GPI)-anchored cell-surface glycoprotein that is highly expressed at the surface of epithelial ovarian cancer cells." (PMID 37108289, 2023). "In ovarian cancer, CAR-T cells target folate-receptor alpha (FRα), mesothelin, MUC-1, and HER2 have been widely investigated." (PMID 36275669, 2022). "For instance, Zhen et found that folate receptor 1 (FOLR1) and mesothelin (MSLN) are specifically highly expressed in ovarian cancer cells by screening the GEO database." (PMID 36275669, 2022). "OTL38, which is a folate receptor-alpha-targeted NIR tracer, has allowed for occult lesion detection in 48% of patients with ovarian cancer that would have otherwise been missed using current conventional techniques." (PMID 34002555, 2021). "Dr. Janos Tanyi from the University of Pennsylvania Perelman School of Medicine discussed the current phase 3 trial of the folate receptor alpha (FRa) tracer OTL38 (On Target Laboratories, West Lafayette, Indiana) for ovarian cancer." (PMID 34002555, 2021).